SEC61G (SEC61 translocon subunit gamma)
Diseases named in the same sentence as SEC61G in open-access papers (continued):
Sharing a sentence is not in itself a finding about the gene and the disease.
breast carcinoma (continued). "Besides, Gene Set Enrichment Analysis (GSEA) also demonstrated that high expression of SEC61G was positively correlated with glycolysis, indicating that SEC61G might regulate glycolysis in breast cancer development." (PMID 34039955, 2021). "Previous research has revealed that SEC61G promotes tumorigenesis through the glycolysis and EMT pathways in breast cancer patients." (PMID 38978503, 2024). "The result was consistent with the study in breast cancer, E2F1 bound to the promoter of SEC61G directly and controlled its expression." (PMID 36712687, 2022). "To explore the function of SEC61G in breast cancer, we utilized siRNAs targeting SEC61G to knock down the expression of SEC61G in MCF-7 and MDA-MB-231 cells, which had the highest expression level of SEC61G." (PMID 34039955, 2021). "Knockdown of SEC61G significantly suppressed glycolysis, showing decreased basal ECAR and maximal ECAR in breast cancer cells." (PMID 34039955, 2021). "In comparison with MCF-10A, breast cancer cell lines including SK-BR-3, T47D, MCF-7, BT-549, and MDA-MB-231 had remarkably higher expression of SEC61G, both at protein and mRNA levels." (PMID 34039955, 2021). "Overexpression of SEC61G and its prognostic role was also confirmed in the Nanjing Medical University (NMU) breast cancer cohort." (PMID 34039955, 2021). "Immunohistochemical staining of SEC61G was performed and the expression of SEC16G was scored based on the staining intensity in breast cancer tissues." (PMID 34039955, 2021). "We investigated that SEC61G was greater in breast cancer tissues related to adjacent non-tumor tissues through qRT-PCR." (PMID 35154452, 2022). "In the result, we found SEC61 translocon gamma subunit (SEC61G) is remarkably upregulated in breast cancer related with adjacent non-cancerous tissues." (PMID 35154452, 2022). "SEC61G protein in 16-paired breast cancer tissues and adjacent normal tissues was assessed by western blot." (PMID 34039955, 2021). "Whether E2F1/SEC61G contributes to the metastasis of advanced breast cancer and targeting E2F1/SEC61G to improve drug-resistance in breast cancer treatment will be further studied." (PMID 34039955, 2021). "Using Oncomine data, we observed that SEC61G was upregulated in almost all cancer types, compared to normal tissues (p < 0.001, |log2 fold change| > 1.5 in all gene ranks), including breast cancer, kidney cancer, brain and central nervous system cancer, and head and neck cancer." (PMID 34590792, 2021).
glioma (10 papers, 2010 to 2023). A benign or malignant brain and spinal cord tumor that arises from glial cells (astrocytes, oligodendrocytes, ependymal cells). "Based on the ONCOMINE database analysis, we found that the SEC61G gene was highly expressed in many types of tumors, such as brain/CNS cancer, head and neck cancer, and kidney cancer, compared with its expression in normal control tissues." (PMID 34173014, 2022). "Studies from non‐small cell lung cancer and glioma indicate that SEC61G promotes tumor proliferation." (PMID 34590792, 2021). "Up-regulated genes included the glioma related genes SEC61G and LNX1 and the cell cycle related SERTAD1 and CCNH." (PMID 29163818, 2017). "For example, EGFR is generally considered as the driver gene at 7p11, however, SEC61G is recurrently co-amplified and over-expressed in glioma." (PMID 21170331, 2010). "Thus, in addition to EGFR, SEC61G is an amplification target in a large fraction of the gliomas." (PMID 21170331, 2010). "The T cell depletion-related prognostic model was developed based on seven prognostic genes (HSPB1, HOXD10, HOXA5, SEC61G, H19, ANXA2P2, HOXC10) in glioma." (PMID 36531217, 2022). "While induction of the Bcan-Ntrk1 rearrangement readily resulted in high-grade gliomas, we never observed tumours after implantation of Fgfr3-Tacc3, Sec61g-Egfr or Gga2-Prkcb positive cell populations within the timeframe of analysis (150 days)." (PMID 28695888, 2017).
lung cancer (7 papers, 2021 to 2025). A malignant neoplasm involving the lung. "Collectively, these results underscore the pivotal role of SEC61G in reshaping the immune landscape of lung cancer, particularly through its association with M2 macrophage polarization and impaired TLS maturation." (PMID 39990664, 2025). "Previous studies have also implicated SEC61G as an oncogene in lung cancer that contributes to ER stress, cell proliferation, apoptosis resistance, and EGFR activation [10‒13]." (PMID 38978503, 2024). "To further investigate how SEC61G influences lung cancer cell metabolism, we used Seahorse XFe analyzers to evaluate its effects on glycolytic capacity." (PMID 39990664, 2025). "Given the significant upregulation of SEC61G in lung cancer brain metastases, we further investigated its expression in lung cancer cell lines with varying brain metastatic potential." (PMID 39990664, 2025). "The results demonstrated that SEC61G protein levels were significantly higher in brain metastatic lesions than in primary lung cancer tissues." (PMID 39990664, 2025). "Collectively, these results confirm that SEC61G is significantly up-regulated in lung cancer brain metastases, suggesting its potential role as a key regulator and biomarker of metastatic progression." (PMID 39990664, 2025). "Transcriptomic analysis of lung cancer cell lines also showed a significant inverse correlation between SEC61G expression and ubiquitination-related biological processes." (PMID 39990664, 2025). "To confirm the functional impact of SEC61G on glycolysis, we assessed glucose uptake and lactate production in lung cancer cells." (PMID 39990664, 2025). "Overall, SEC61G expression in lung cancer cells significantly influences the immune phenotype of microglia, promoting M2 polarization while inhibiting M1 polarization at the protein level." (PMID 39990664, 2025). "To further confirm the effects of SEC61G on microglial polarization, we manipulated SEC61G expression in lung cancer cells and co-cultured them with HMC3 microglia." (PMID 39990664, 2025). "To further assess the functional interplay between SEC61G and UBE3C, we examined the effects of SEC61G expression changes on PGAM1 levels in lung cancer cell lines." (PMID 39990664, 2025). "This study identifies SEC61G as a pivotal regulator of immune evasion in lung cancer, primarily through promoting M2 macrophage polarization and impairing tertiary lymphoid structures (TLS) maturation." (PMID 39990664, 2025). "In summary, SEC61G physically interacts with PGAM1 in lung cancer cells, and both proteins exhibit cytoplasmic co-localization, supporting their functional association." (PMID 39990664, 2025). "Overall,HNRNPA2B1 andIGF2BP3 are potential interacting genes related to the involvement of SEC61G in the progression of lung cancer, but further experimental validation is needed." (PMID 38978503, 2024). "The present study aimed to investigate the role of SEC61G in regulating lung cancer cell migrationin vitro." (PMID 38978503, 2024). "Recurrent EGFR fusions included CCT6A-EGFR fusions in two cases of lung cancer (2/13, 15.4%) and intergenic EGFR-SEC61G fusions, occurring at intergenic regions downstream of SEC61G, in three cases of gastric cancers and one case of lung cancer." (PMID 36369474, 2022). "Thus, we identified SEC61G and 14 other genes as potential drivers of lung cancer brain metastasis, laying the groundwork for further mechanistic studies." (PMID 39990664, 2025). "To investigate whether SEC61G regulates PGAM1 at the protein level, we assessed the stability of PGAM1 in SEC61G-overexpressing lung cancer cells using the protein synthesis inhibitor cycloheximide (CHX)." (PMID 39990664, 2025). "Although these findings highlight SEC61G as a potential molecular marker and mediator of brain metastasis, additional studies are required to determine whether SEC61G acts as a driver gene in lung cancer brain metastasis." (PMID 39990664, 2025).
lung cancer (continued). "Consistent with our results, other PSMC signature-related genes, including LDHA, SEC61G, PLEK2, and C1QTNF6, have been shown to be risk genes in lung cancer in vitro, mediating the development, growth, and metastasis of lung cancer." (PMID 36699466, 2022). "Additionally, vitro experiments verified the biological behaviors of SEC61G in lung cancer." (PMID 34774014, 2021). "Therefore, SEC61G might participate in the E2F-related pathway to regulate the cell cycle of lung cancer cells." (PMID 34774014, 2021). "The immune profiling of SEC61G expression revealed distinct patterns of immune cell infiltration and tertiary lymphoid structures (TLS) maturation in lung cancer samples." (PMID 39990664, 2025). "In conclusion, this study reveals that SEC61G plays a pivotal role in regulating microglial polarization and shaping the TME in lung cancer brain metastases." (PMID 39990664, 2025). "To substantiate these findings, we collected 15 primary lung cancer tissue samples with brain metastasis and 15 lung cancer tissues without brain metastases for immunohistochemical (IHC) analysis of SEC61G expression." (PMID 39990664, 2025).
kidney cancer (6 papers, 2021 to 2023). Primary or metastatic malignant neoplasm involving the kidney. "For kidney cancer SEC61G knockdown significantly promoted cell apoptosis in a caspase-dependent manner." (PMID 36712687, 2022). "For instance, we observed high expression of the SEC61G gene in kidney cancer tissues in six studies." (PMID 34173014, 2022). "SEC61G knockdown significantly inhibits cell proliferation, migration and invasion; therefore it may serve as a biomarker for kidney cancer." (PMID 37489460, 2023).
gastric cancer (5 papers, 2021 to 2022). A primary or metastatic malignant neoplasm involving the stomach. "However, genomic copy-number aberrations of SEC61G seem to be associated with the expression of SEC61G in gastric cancer (R = 0.93, p < 0.01)." (PMID 34173014, 2022). "Genome-wide analysis of gene expression in gastric cancer has identified that SEC61G was highly expressed in gastric cancer, which was further confirmed by immunohistochemical staining." (PMID 34039955, 2021).
hepatocellular carcinoma (5 papers, 2021 to 2026). A malignant tumor that arises from hepatocytes. "In this study, GO and KEGG analysis indicated that SEC61G was significantly associated with the proliferation-associated biological process such as DNA replication, cell cycle and cell division, which is consistent with previous research in hepatocellular carcinoma." (PMID 34774014, 2021). "SEC61G is an oncogene in hepatocellular carcinoma (HCC), a common malignant tumor worldwide." (PMID 41662387, 2026).
lung adenocarcinoma (5 papers, 2021 to 2025). A carcinoma that arises from the lung and is characterized by the presence of malignant glandular epithelial cells. "To further investigate the prognostic value of SEC61G expression in lung adenocarcinoma (LUAD), we analyzed two independent cohorts: the TCGA-LUAD dataset (n = 535) and a LUAD tissue microarray cohort (n = 79)." (PMID 39990664, 2025). "SEC61G participates in endoplasmic reticulum stress by interacting with CREB3 to promote the malignant progression of lung adenocarcinoma." (PMID 37491302, 2023). "The results showed that SEC61G was highly expressed in lung adenocarcinoma tissue compared with normal tissue (p < 0.001)." (PMID 34774014, 2021). "Lung adenocarcinoma studies have shown that the (SEC61G) is overexpressed in several tumors and could serve as a potential prognostic marker or target for the diagnosis and treatment of HC." (PMID 39000458, 2024). "To explore the impact of SEC61G on M1 and M2 polarization markers in microglia, we overexpressed SEC61G in H2030 and PC9 lung adenocarcinoma cells and co-cultured these cells with HMC3 microglia." (PMID 39990664, 2025). "However, the correlation between SEC61G and lung adenocarcinoma (LUAD) remains unclear." (PMID 34774014, 2021). "However, the potential correlation between SEC61G and lung adenocarcinoma remains unclear." (PMID 34774014, 2021). "However, the potential correlation between SEC61G and lung adenocarcinoma has not been characterized." (PMID 34774014, 2021).
head and neck squamous cell carcinoma (4 papers, 2021 to 2022). A squamous cell carcinoma that arises from any of the following anatomic sites: lip and oral cavity, nasal cavity, paranasal sinuses, pharynx, larynx, and salivary glands. "A total of 2275 co-expressed genes related to SEC61G in HNSCC (Head and Neck Squamous Cell Carcinoma (TCGA, Firehose Legacy)) were identified, of which 1,041 genes were positively correlated." (PMID 36712687, 2022). "However, the correlation between SEC61G and disease prognosis in head and neck squamous cell carcinoma (HNSCC) remains unclear." (PMID 34590792, 2021).
non-small cell lung carcinoma (3 papers, 2021 to 2025). A group of at least three distinct histological types of lung cancer, including non-small cell squamous cell carcinoma, adenocarcinoma, and large cell carcinoma. "For example, the binding of lncRNA LINC02418 and miR-4677-3p (microRNA-4677-3p) was associated with the expression of SEC61G in NSCLC (non-small cell lung cancer) cells." (PMID 34173014, 2022). "Previous in vitro functional assays revealed that SEC61G knockdown inhibited non-small-cell lung cancer cell proliferation and invasion while promoted apoptosis." (PMID 34093796, 2021). "This study systematically investigates the role and molecular mechanisms of SEC61G in non-small cell lung cancer (NSCLC) brain metastases, highlighting its critical role in promoting metastases through metabolic reprogramming and immune microenvironment remodeling." (PMID 39990664, 2025).
breast tumor (2 papers, 2021 to 2022). "To know more about SEC61G and breast tumor, we examined the association of SEC61G with clinicopathologic features." (PMID 35154452, 2022). "The immunohistochemistry (IHC) from the Human Protein Atlas database also verified that the SEC61G protein was over-expressive in breast tumors." (PMID 35154452, 2022). "Xenograft breast tumor model revealed that knockdown of SEC61G inhibited breast tumor development in vivo." (PMID 34039955, 2021).
colorectal cancer (2 papers, 2023 to 2025). A primary or metastatic malignant neoplasm that affects the colon or rectum. "In colorectal cancer, six genes were positively correlated: ANLN, ACOT7, OSBPL3, SEC61G, DDX56, and TRIM10." (PMID 40765570, 2025).
lymph node metastases (2 papers, 2024 to 2025). "In the LUAD tissue microarray cohort, high SEC61G protein expression was significantly associated with several adverse clinical characteristics, including advanced patient age (P = 0.013), T stage (P < 0.001), M stage (P < 0.001), and the number of lymph node metastases (P = 0.013)." (PMID 39990664, 2025). "Our findings indicated that SEC61G is positively correlated with lymph node metastasis but negatively correlated with B cells, CD4+ T cells, macrophages, and dendritic cells." (PMID 38978503, 2024).
Alzheimer disease (1 paper, 2023). A progressive, neurodegenerative disease characterized by loss of function and death of nerve cells in several areas of the brain leading to loss of cognitive function such as memory and language. "SEC61G is among the nine circadian-related genes identified related to circadian rhythm disruption, which is critical in the pathogenesis of Alzheimer’s disease." (PMID 37489460, 2023).
Balkan endemic nephropathy (1 paper, 2022). "The expression of SEC61G was reportedly associated with IFN-K immunosuppressive therapy for lupus nephritis, while the methylation modification of SEC61G was related to Balkan endemic nephropathy." (PMID 34173014, 2022).
brain tumors (1 paper, 2022). "In addition to in brain tumors, we also detected a high expression level of SEC61G in other types of tumors." (PMID 34173014, 2022).
diabetes (1 paper, 2021). "Previous studies have also revealed that SEC61G participates in the regulation of multiple disease states including diabetes, neurodegeneration, and cancer." (PMID 34093796, 2021).
hepatitis B virus (1 paper, 2019). "Six IA genes, APOB, IMPDH1, SEC61G, IQGAP2, TAGAP, and IGKV4-1, were dysregulated (differential expression, p < 0.05) in only tumor samples of drinkers without hepatitis B virus (HBV) infection as compared to pure normal samples (from nondrinkers)." (PMID 31480259, 2019).
hypopharyngeal squamous cell carcinoma (1 paper, 2024). "Targeting the E2F1/SEC61G pathway increased response to chemotherapy in hypopharyngeal squamous cell carcinoma through immune response." (PMID 38689649, 2024).
keratinization (1 paper, 2021). The process in which the cytoplasm of the outermost cells of the vertebrate epidermis is replaced by keratin. "SEC61G expression correlated to the degree of pathological keratinization, that is, the proportion of SEC61G‐positive samples patients with keratinization was higher than in patients with non‐keratinization (p = 0.009)." (PMID 34590792, 2021).
larynx tumor (1 paper, 2022). "In the TCGA database, compared with the 40 normal tissues samples, SEC61G was highly expressed in 520 primary HNSCC tissue samples, mainly including 133 tongue tumor samples and 117 larynx tumor samples." (PMID 34173014, 2022).
metastatic tumor (1 paper, 2025). "Furthermore, the expression level of SEC61G was markedly elevated in brain metastatic tumor cells compared to primary tumor cells, with statistical significance." (PMID 39990664, 2025).
oral squamous cell carcinoma (1 paper, 2023). "In the present study, although there is currently a lack of systematic assays to identify the underlying molecular mechanisms of SEC61G in oral squamous cell carcinoma (OSCC), we utilized Gene Set Enrichment Analysis (GSEA) to gain further insights into its potential role in the development of OSCC." (PMID 37893092, 2023). "Notably, our study findings obtained through both bioinformatics analysis and immunohistochemistry (IHC) indicated that increased SEC61G expression levels are significantly correlated with poorer clinicopathologic factors in oral squamous cell carcinoma (OSCC)." (PMID 37893092, 2023).
oropharyngeal carcinoma (1 paper, 2021). Carcinoma, predominantly squamous cell, arising from the epithelial cells of the oropharynx. "Finally, we validated SEC61G overexpression and its prognostic value in 91 oropharyngeal cancers (OPCs)." (PMID 34590792, 2021). "SEC61G expression in oropharyngeal cancer tissues was higher than in normal adjacent tissues." (PMID 34590792, 2021). "Finally, immunohistochemistry was used to detect SEC61G expression in oropharyngeal carcinoma." (PMID 34590792, 2021). "Furthermore, SEC61G protein expression was also an independent prognostic factor of OS (HR = 2.46, 95% CI: 1.15–5.28, p = 0.021) and progression‐free survival (HR = 2.82, 95% CI: 1.36–5.85, p = 0.005) for oropharyngeal cancer." (PMID 34590792, 2021).
Parkinson disease (1 paper, 2021). A progressive degenerative disorder of the central nervous system characterized by loss of dopamine producing neurons in the substantia nigra and the presence of Lewy bodies in the substantia nigra and locus coeruleus. "Functional annotations indicated that SEC61G is involved in pathways related to translation and regulation of SLITs/ROBOs expression, SRP-dependent co-translational protein targeting to the membrane, nonsense-mediated decay, oxidative phosphorylation, and Parkinson's disease." (PMID 34093796, 2021).
thyroid carcinoma (1 paper, 2021). "All tumor tissues presented in the TIMER database except the thyroid carcinoma showed higher SEC61G expression compared with the corresponding normal tissues." (PMID 34774014, 2021).